MMP9 (matrix metallopeptidase 9)
Diseases named in the same sentence as MMP9 in open-access papers (continued):
Sharing a sentence is not in itself a finding about the gene and the disease.
tumor (continued). "Rechallenge experiments attempting to assess the effects of MMP-9 inhibition on immunological memory were not feasible as no NeuT tumor regrowth was observed in those mice, perhaps due to the age of the animals or the potential for immunological memory to the rat NeuT antigen protein." (PMID 30500835, 2018). "This design of MMP-9 biosensor can be used for the in vivo imaging of MMP-9 activity, which is especially valuable for investigating the biological role of MMP-9 during pathological processes such as tumor development, cancer metastasis and cancer angiogenesis." (PMID 30262739, 2018). "Although the MMP-9 regulation is not related to transformation of the normal cells into tumoral, it plays an essential role in degrading of type IV collagen (the major component of the basement membrane), thus promoting tumor invasion." (PMID 30509240, 2018). "Besides, a possible explanation for the role played by KiSS1 in cancer biology can be extrapolated from the correlation between KiSS1 and matrix metalloproteases (MMPs), particularly MMP-9 and MMP-2, whose significance in tumor invasion and metastasis formation is well known." (PMID 29721201, 2018). "Effects of FAK kinase inhibition may be attributed to attenuated cell migration, invasion, and lack of tissue remodeling enzymes such as MMP2, MMP9 and uPA, which may impact tumor metastasis." (PMID 28915654, 2017). "Also, RNAi-based S100A4 could directly reduce the expression of VEGF and MMP-9, and lead to a decrease in ATC cell invasion and tumor angiogenesis." (PMID 29069865, 2017). "MMP-2 and MMP-9 could degrade the ECM and basement membrane collagen of blood vessels then promote tumor cell invasion and matastasis, while vascular endothelial growth by binding to VEGF receptor to promote angiogenesis, thus participating in the development and progression of tumors." (PMID 29156710, 2017). "We found that in vitro treated 4T1 cell line with 25 μg/mL BDM significantly reduced the MMP‐2, MMP‐9 activities and adhesion of 4T1 cells to collagen I, fibronectin, and laminin which inhibited 77.7 % tumor incidence after inoculation without any effect in viability of cell line." (PMID 28211615, 2017). "In addition, silencing RARα inhibited the expression of PCNA, CyclinB1, CyclinD2, CyclinE, MMP9 and MDR1 and enhanced p21 expression, that may play critical roles in tumor growth, invasion, drug resistance." (PMID 28035062, 2017). "Ultimately, we aim to investigate whether the increased number of M2 macrophages was correlated with high expression of MMP9 and high MVD, which contributes to the tumor aggressiveness and angiogenesis, and facilitates the occurrence and progression of Kazakh ESCC." (PMID 28423526, 2017). "Furthermore, tumor cells recruit MMP-2- and MMP-9-producing neutrophils and macrophages." (PMID 29112161, 2017). "Study has shown that the expression of MMP-2 and MMP-9 is closely related to cancer angiogenesis; tumor cells which can secrete MMP-2 and MMP-9 have high invasion and metastases ability, drugs can also be used to inhibit the growth of tumor cells through lowering the activity of MMP-2 and MMP-9." (PMID 28978315, 2017). "Interestingly, hMDA-7 was shown to suppress tumor cell invasion and migration by down regulating MMP-2, MMP-9, and VEGF expression, although the detailed mechanisms remain unclear." (PMID 28985230, 2017). "Regarding tumor stage we found a not significant increase in MMP-9 levels with advanced stages." (PMID 29207990, 2017). "Moreover, a marked reduction in vascular endothelial growth factor (VEGF) expression, CD31+ blood vessels, CD4+ Foxp3+ Treg cells and the expression of MMP-2, MMP-9, MMP-13 and C-X-C motif chemokine receptor 4 (CXCR4) in the tumour stroma were observed in the Smad3−/− tumour microenvironment." (PMID 28262747, 2017).
tumor (continued). "Aberrant activation of NF-κB pathway is observed in a variety of tumor types, which regulates a range of tumorgenic processes, including proliferation, invasion, metastasis and angiogenesis, by transcriptionally activating numerous target genes, such as CCND1, MYC, MMP9 and VEGF in cancer cells." (PMID 29044221, 2017). "In addition, CAPN2-OV could enhance N-cadherin, Vimentin and MMP9 protein level in CAKI-2 cells, which highlights the promoting role of CAPN2 in tumor metastasis in RCC." (PMID 29228653, 2017). "Therefore, based on these data, we hypothesized that propoxur could reduce tumor cell migration and invasion through ROS-dependent secretion and activation of MMP-2 and MMP-9." (PMID 29152067, 2017). "Moreover, ECM degradation by MMP-9 releases VEGF, the potent promoter of tumor angiogenesis." (PMID 28388546, 2017). "Importantly, downregulation of WISP1 in vivo also induced decrease in expression of ICAM-1, VCAM-1, VEGFC, MMP-2, MMP-9 and increase in E-cadherin, suggesting that WISP1 downregulation not only inhibited tumor growth but also suppressed tumor metastasis in vivo." (PMID 27409174, 2016). "Several studies have shown the MMP-9 inhibition by doxycycline, so, before analyzing the expression of MMP-9 in the current study, we assumed that MMP-9 would be inhibited or reduced by doxycycline which could lead to the increased angiogenesis and tumor growth." (PMID 26998758, 2016). "Neither LCN2 nor MMP9 shows tumor-specific expression, and the release of these proteins into the circulation from other tissues of origin might therefore change as an adverse response to therapy." (PMID 27461255, 2016). "Upon depletion of Rab40b, the lack of MMP2 and MMP9 targeting could lead to reduced angiogenesis, thus inhibiting tumor growth." (PMID 27789576, 2016). "In spite of these limitations, our meta-analysis result revealed that high MMP-9 expression in tumor tissue but not serum could be an implication of advanced tumor stage and poor prognosis of NSCLC." (PMID 26918342, 2016). "In addition, we show that CLU, MMP-9 and VEGF can also be detected at the NPC tissues, which could open new avenues for both the tumor metastasis and the development of novel immunotherapeutic strategies in NPC." (PMID 26716898, 2016). "14,15-EET could promote MMP-9 expression in tumor cells, but did not increase the production of active MMP-9 (our unpublished data)." (PMID 27270316, 2016). "Furthermore, MMP9 was also highly expressed in CSC-containing basal-cell-like cell layer located at the invasive front of HNSCC tumor, but not in basal cell layer of normal mucosa, thus facilitating tumors invasion via degradation of ECM." (PMID 27570510, 2016). "In addition, when cancer cells with TM4SF1 overexpression were injected into nude mice, this increased the expression of genes related to angiogenesis (uPA, MMP-2, MMP-9 and VEGF), decreased the expression of TIMP (an inhibitor of MMP), and led to promotion of angiogenesis and tumor growth." (PMID 27153056, 2016). "For SAS cells, the gene expression of MMP2, MMP9 and MMP14 in ALG-CS was significantly higher than that in ALG (for MMP2 P = 0, for MMP9 P = 0.04634, for MMP14 P = 0.00194), which indicated that ALG-CS could further enhance MMP gene expression in tumor cells compared with ALG." (PMID 27432752, 2016). "MMP-9 is mostly secreted by inflammatory cells such as macrophages, rather than by tumor cells." (PMID 27271600, 2016). "Therefore, HOTAIR may promote tumor aggressiveness through the upregulation of VEGF and MMP-9 and EMT-related genes." (PMID 25405331, 2015). "Tie2-expressing monocytes (TEMs) have been found in various human tumors, to form tumor blood vessels and express several proangiogenic factors such as basic fibroblast growth factor (b-FGF), vascular endothelial growth factor (VEGF), and matrix metalloproteinase-9 (MMP-9)." (PMID 26599011, 2015).
tumor (continued). "Furthermore, the results of immunohistochemical analysis on human HNSCC tumor samples demonstrated that garcinol in combination with cisplatin significantly suppressed NF-κB (p65), COX-2, VEGF, and MMP-9, and such downregulation was more impressive than either garcinol or cisplatin alone." (PMID 25762616, 2015). "However, in other models and clinical trials, inhibition of MMP-9 was not effective at reducing tumor growth." (PMID 26819959, 2015). "Interestingly, fucoidan can reduce the tumor-induced VEGF expression as well as the expression of MMP-2, MMP-9 and NF-κB in lung tissues, suggesting fucoidan restrains cancer cells from invasion and metastasis through suppressing epithelial cell proliferation and blood vessel formation." (PMID 25854641, 2015). "Neither MMP2 nor MMP-9 activity was detected in tumor cells." (PMID 25885552, 2015). "Furthermore, when including all tumor types, tumor MMP-9 expression was not an independent prognostic factor for the additional outcomes tested." (PMID 25888323, 2015). "The critical step in tumor invasion and metastasis is reportedly the breakdown of the ECM, which requires activation of proteolytic enzymes such as MMPs, particularly MMP-2 and MMP-9, as elevated levels of these are well documented to indicate an invasive phenotype." (PMID 25605016, 2015). "Thus, MMP-3 might promote spontaneous metastasis in 4T1.2 and EO771.LMB tumours in part via proteolytic processing of PTHLH and MMP-9." (PMID 25633981, 2015). "However, among patients with adenocarcinoma, there was a significant negative correlation between tumor MMP-9 expression and both DFS (p = 0.003) and OS (p = 0.033)." (PMID 25888323, 2015). "Moreover, the expression levels of the osteoclast gene MMP9 in RAW264.7 cells reflected the lack of differentiation signaling cues upon NOG/FST knockdown in the tumor cells." (PMID 25973542, 2015). "Further, levels of related MMPs including MMP1, MMP8, MMP14, MMP2 and MMP9 which have previously been shown to affect tumor cell invasion were not evaluated in these studies and could compensate for MMP13 levels." (PMID 25880591, 2015). "Additionally, we examined whether the expression of the invasion proteins MMP-2 and MMP-9 was suppressed by blocking mTOR signaling in secondary NPC tumors and whether tumor sizes and weights were also affected." (PMID 26202311, 2015). "Importantly, we showed that these two C3f-derived fragments detected in serum were primarily generated by tumor-resident, but not blood-circulating, MMP-9." (PMID 25788424, 2015). "Finally, secretions were profiled in the conditioned medium of patient-isolated TEM and revealed that tumor TEM are paracrine inducers of tumor angiogenesis by releasing high levels of angiogenic factors (i.e. VEGF, bFGF, and ANG-1) and MMP9 (matrix metalloproteinase 9)." (PMID 25768678, 2015). "However, expressions of angiogenesis-related genes such as HIF1α, VEGF and tumor invasion-related genes like MMP2, MMP9, E-cadherin and β-catenin were increased by either carbon ion beam or X-ray irradiation alone and/or in combination with gemcitabine compared to." (PMID 25849939, 2015). "Additionally, tumor volume and weight are significantly inhibited through the suppression of Akt, mTOR, and Stat3, accompanied by a decrease in the expression of MMP-2 and MMP-9 in vivo." (PMID 26202311, 2015). "In other words, an IHC score of less than 10 was defined as an absence of tumor MMP-9 expression." (PMID 25888323, 2015). "Moreover, the expression of E-cadherin (CDH1), a negative-related protein for tumor invasion, was clearly reduced, and two positive-related proteins for tumor invasion and metastasis, MMP-2 and MMP-9, were increased in expression in the IgGhigh MDA-MB-231 cells." (PMID 26472025, 2015).
tumor (continued). "Thus, in this heterologous mouse model for Theileria-transformed macrophage dissemination ectopic expression of Flag-Δ169-c-Jun that diminishes MMP9/ADAM19 and increases TIMP3 expression led to ablation of tumour dissemination by the engineered attenuated line." (PMID 25375322, 2014). "The normal breast tissue adjacent to the tumor was negative for MMP-9 expression." (PMID 24993803, 2014). "Moreover, we found that RANKL could promote the expression of MMP1, MMP3 and MMP9, which indicated that increased expression of MMPs was involved in the process that RANKL promoted tumor invasion and migration via NF-κB pathway." (PMID 25268581, 2014). "In addition, to assess whether downregulation of pro-MMP-9, pro-MMP-2, uPA expression in serum-free tumor conditioned medium affects the degradation of the extracellular matrix, radiolabeled type IV collagen degradation assay was performed." (PMID 25176506, 2014). "This suggests that MMP-9 and IDO may play similar roles in tumor-induced NK cell dysfunction." (PMID 25274283, 2014). "When neutrophils were recruited to peritoneal cavity with CXCL1-expressing cells (C-PC, non-inflammatory), the neutrophils from tumor-bearing mice and pG/pI6-mice showed a protumor phenotype, characterized by higher expression of Bv8 and Mmp9 as well as lower expression of Rab27a and Trail." (PMID 25587026, 2014). "For instance, in genetically-engineered mice, although the lack of MMP-2, -7, or -9 in CR2-Tag mice all led to reduced tumor vascularity, the loss of MMP-2 conferred decreased lung metastasis and increased survival, while the lack of MMP-9 led to increased perivascular invasion." (PMID 24978435, 2014). "MMP-9 protein was localized to the cytoplasm of both tumor and stromal cells.We correlated MMP-9 expression with clinicopathological characteristics, including histological type, tumor size, histological grade, lymph node metastasis and ER, PR and HER2/neu status." (PMID 24845596, 2014). "MMP-9 expression at the margin of the resection did not significantly differ from the expression in the main tumor mass, but, in the group of tumors with positive margins, MMP-9 was significantly more strongly expressed overall versus the group of tumors with negative resection margins (P = 0.0121)." (PMID 25097794, 2014). "However, the roles of MMP9 and MMP2 in the heightened invasion upon anti-angiogenic therapy might be only one force behind this phenomenon, and TEMs could secrete other tumor-remodeling molecules that contribute to the adaptive response." (PMID 24809734, 2014). "High amounts of MMPs, particularly MMP-9, degrade the ECM, release and activate VEGF, and allow migration of cells (including infiltration of leukocytes, spreading of metastatic tumor cells, and integration of pericytes and endothelial cells into the tumor vasculature)." (PMID 23874303, 2013). "CD44 and MMP-9, however, did not co-localize on these tumor bleb structures." (PMID 24194929, 2013). "Interestingly, only invasive EMPD possessed substantial numbers of CD163+ M2 macrophages and MMP-9+ cells, B7H1+ cells, and ARG1+ cells around the tumor, whereas few CD163+ M2 macrophages, MMP-9+ cells, B7H1+ cells, and ARG1+ cells were observed in noninvasive EMPD." (PMID 23606867, 2013). "We found that MMP9 expression was significantly reduced only in the decitabine-treated control tumors (scrambled control shRNA, or scr-shRNA), but not in tumors generated with PKD1 shRNA cells or in saline-treated tumors, in which local tumor cell invasion was observed." (PMID 23971832, 2013). "Moreover, in line with our observations in TAMs, tumor-cell–conditioned medium induced Hif1α, VefgA and Mmp9 expression in control but not in Mφ-c-Myc-KO BMDMs." (PMID 23028984, 2012).
tumor (continued). "In this study, we aimed to correlate the expression of DSPP, OPN and BSP as well as three SIBLING-partners, matrix metalloproteinase-2 (MMP-2), matrix metalloproteinase-3 (MMP-3), and matrix metalloproteinase-9 (MMP-9), at histologically-negative margins of OSCCs with tumor recurrence." (PMID 22410369, 2012). "The evidence that expression of KGF and MMP-9 was correlated with liver metastasis may indicate that the KGF/KGFR pathway induces MMP-9 expression, and MMP-9 in turn destroys the basement membrane of tumor vessels to lead to liver metastasis." (PMID 22159401, 2012). "Although lymphatic/vascular invasion (LVI) and tumor size (T) were also independently predictive when included with MMP-9 in multivariate analyses, their predictive association was not as strong as that of MMP-9." (PMID 22410369, 2012). "MMP-9 has been demonstrated in neutrophils and macrophages of the tumor tissue, whereas the tumor cells themselves were negative, suggesting that MMP-9 might be an important part of the inflammatory response elicited by the malignant cells." (PMID 22159423, 2012). "In the absence of MMP9, tumor vessels displayed a 50% lower coverage with pericytes." (PMID 24213237, 2012). "While IL-8 resulted to be expressed mainly by inflammatory cells infiltrating the adenocarcinoma in advanced stage of progression, and apparently not by cancer cells (data not shown), MMP-9 was clearly produced in large amount by both macrophages and tumor cells." (PMID 22848630, 2012). "We hypothesised previously that the poor prognosis found for patients with very low tumour MMP-9 levels is possibly due to the lack of infiltrating leukocytes, which may possess anti-cancer effects." (PMID 22472880, 2012). "Matrix metalloproteinase-9 (MMP-9) is one of the proteases that has the preferential ability to degrade denatured collagens (gelatin) and collagen type IV, the 2 main components of basement membranes and therefore plays a critical role in tumor progression and metastasis." (PMID 21535879, 2011). "However, the tumor cells invasiveness and protein levels of MMP-9 were no statistical difference in ER-positive cells MCF-7." (PMID 21595884, 2011). "Since the activation and secretion of MMP-9, a key enzyme in the degradation of extracellular matrices that promotes tumor cell invasion, are significantly induced by HRG in SKBR3 cells, we performed a zymogram assay to investigate whether MMP-9 is involved in the regulation of cell invasion." (PMID 21080941, 2010). "However, in sections of ectopic tumours treated with Dz13, both MMP-2 and MMP-9 were downregulated." (PMID 20334687, 2010). "The resulting changes in gene expression facilitated by the loss of nuclear syndecan-1 could explain how heparanase enhances expression of MMP-9, VEGF, tissue factor and perhaps other effectors that condition the tumor microenvironment to promote an aggressive cancer phenotype." (PMID 19305494, 2009). "In this perspective, it had been postulated that CD44/MMP-9 complex formation on the cell surface might signify as a novel motility-enhancing signal for tumor cells which eventually contributes their invasiveness." (PMID 19290049, 2009). "MMP-9 is not constitutively expressed by endothelial cells, but it may be induced in response to several factors, including the tumour promoter chemical phorbol myristate acetate (PMA), cytokines or stress." (PMID 18782185, 2008). "EMMPRIN expression showed a significantly positive association with tumour size, depth of invasion, lymphatic invasion, expression of ki-67, MMP-2, MMP-9 and VEGF of tumours (P<0.05), but not with lymph node metastasis, UICC staging or differentiation (P>0.05)." (PMID 17088917, 2006). "Interestingly, the MMP-9 null fibroblast had reduced in vivo effect on FaDu tumor growth compared to WT fibroblasts (48% less tumor volume) despite the absence of observed differences for MMP-9 null fibroblasts in previous in vitro experiments." (PMID 16515711, 2006).